REG3A (regenerating family member 3 alpha)
Diseases named in the same sentence as REG3A in open-access papers (continued):
Sharing a sentence is not in itself a finding about the gene and the disease.
gastric tumors (1 paper, 2019). "Furthermore, expression of mRNA transcripts for the bona fide STAT3‐target genes Socs3, Icam1, and Reg3a, which are both induced by IL11 in gastric tumors, were significantly decreased in tumors from bazedoxifene‐treated animals." (PMID 30885958, 2019).
head and neck squamous cell carcinoma (1 paper, 2022). A squamous cell carcinoma that arises from any of the following anatomic sites: lip and oral cavity, nasal cavity, paranasal sinuses, pharynx, larynx, and salivary glands. "In head and neck squamous cell carcinoma (HNSCC), cells transfected with REG3A exhibited significantly decreased cell proliferation and higher chemosensitivity and/or radiosensitivity; REG3A expression was significantly associated with prolonged survival." (PMID 34811636, 2022).
hip osteoarthritis (1 paper, 2022). "This candidate locus is strongly associated with hip osteoarthritis (OA), suggesting REG3A may influence canine hip OA through MAPK pathway signaling." (PMID 36531249, 2022).
Hyperinsulinemia (1 paper, 2023). An increased concentration of insulin in the blood. "We report here that increase of REG3A, both as a transgene and as a recombinant protein, controls elevated basal insulin levels during aging, high-fat feeding, and in obese ob/ob mice and prevents glucose-induced hyperinsulinemia." (PMID 36918710, 2023). "Our results suggest that a therapeutic approach based on REG3A could break the vicious circle between hyperinsulinemia and altered signaling by oxidative stress, which, if not controlled, contributes to disease progression." (PMID 36918710, 2023). "Such a REG3A-mediated mechanism of action most likely promotes induction of gp130-AMPK signaling and thus bypasses the typical impairment of insulin signaling, leading to minimization of the amount of insulin needed to control blood glucose and reduce hyperinsulinemia." (PMID 36918710, 2023).
intestinal infection (1 paper, 2023). "Reg3a and Reg3g are highly expressed upon bacterial colonization of the gut and during intestinal infection and inflammation, thereby contributing to the spatial segregation of intestinal bacteria and the epithelium." (PMID 37170509, 2023).
ischemic stroke (1 paper, 2024). A stroke disorder caused by obstruction of blood flow to the brain, due to thrombotic (local blood clot formation) or embolic (due to a blood clot or other material traveling from another site) event. "Previously, we published that REG3A expression in ischemic stroke patient systemic blood, during mechanical thrombectomy (MT), is significantly associated with inflammatory cytokines and patient function on admission." (PMID 39337456, 2024). "In the context of ischemic stroke, very little has been published about REG3A." (PMID 39337456, 2024).
Jaundice (1 paper, 2023). Yellow pigmentation of the skin due to bilirubin, which in turn is the result of increased bilirubin concentration in the bloodstream. "Tonack and collaborators have also looked for potential plasma biomarkers for PDAC and found some candidates, but they are associated with jaundice, showing the highest sensitivity of ITIH3, C5, A1BG, PIGR, and Reg3A in this condition." (PMID 37628784, 2023).
metabolic syndrome (1 paper, 2023). A cluster of metabolic risk factors for CARDIOVASCULAR DISEASES and TYPE 2 DIABETES MELLITUS. "Overall, this study suggests that REG3A, by mitigating oxidative stress, which is enhanced by metabolic syndromes triggered by Western diets, preserves the function of selective metabolic pathways involved in glucose homeostasis, namely, in this study, gp130-dependent AMPK activation." (PMID 36918710, 2023).
tumor (29 papers, 2011 to 2025). "Elevated REG3A expression has been reported in certain human tumor types and has been associated with cancer initiation and progression in various experimental models." (PMID 40723277, 2025). "Regenerative gene protein (REG3A) overexpression is associated with excessive proliferation, invasion, migration, distant metastasis, and tumor aggressiveness." (PMID 36105933, 2022). "Overexpression of REG3A is associated with excessive proliferation, invasion, migration, distant metastasis and tumor invasiveness." (PMID 36591515, 2022). "Downregulation of REG3A caused by siRNA significantly decreased the proliferation of tumor cells in vitro (both p < 0.05)." (PMID 31940813, 2020). "Further clinical characteristics analysis showed that higher expression level of REG3A was associated with bigger tumor size, poorer differentiation, higher tumor stage and lower survival rate." (PMID 26646797, 2016). "The expression of REG3A is dysregulated across multiple human solid tumors, yet its functional role in these cancers remains highly nuanced and varies depending on tumor type and biological conditions." (PMID 40723277, 2025). "Only through such integrative approaches can the full spectrum of REG3A’s oncogenic and tumor-suppressive functions be defined, paving the way for informed translational applications in oncology." (PMID 40723277, 2025). "A number of studies have reported marked overexpression of REG3A in tumor tissue compared to adjacent non-tumor liver, validated at both mRNA and protein levels." (PMID 40723277, 2025). "Elevated REG3A correlates with aggressive features such as larger tumor size and vascular invasion, and is found in 24–79% of HCC cases, depending on the detection method." (PMID 40723277, 2025). "Supporting this, mouse livers expressing wild-type REG3A and non-tumor tissues from HCC patients show reduced UDP-GlcNAc and global O-GlcNAcylation." (PMID 40723277, 2025). "REG3A exerts pleiotropic functions that extend beyond the tumor itself, influencing organ-level physiology, host–microbiota interactions, and metabolism, factors poorly represented in in vitro systems." (PMID 40723277, 2025). "The following sections will examine the implications of REG3A’s dual functionality in inflammation, host–microbe interactions, and tumor biology." (PMID 40723277, 2025). "Depending on the tumor type and microenvironment, REG3A can either support tumor growth or exert tumor-suppressive effects." (PMID 40723277, 2025). "In some tumor types, REG3A fosters malignant progression by enhancing cell survival, proliferation, and invasiveness." (PMID 40723277, 2025). "This potential functional reprogramming highlights the variable role of REG3A in cancer, influenced by factors such as tissue origin, cancer subtype and molecular profile, the pathological status of surrounding tissue, tumor stage, and the immune landscape." (PMID 40723277, 2025). "In our preliminary studies, the single-chain variable fragment (scFv) against Reg3A and Reg4, two of the most commonly overexpressed Reg proteins in tumors, have demonstrated significant anti-tumor effects." (PMID 39857608, 2024). "Current research primarily focused on the detection of Reg3A and Reg4 levels in serum and tumor tissues, with superior accuracy and sensitivity compared to the existing biomarkers, making them promising novel indicators for both diagnosis and prognosis." (PMID 39857608, 2024). "In both in vivo and in vitro studies, knockout of Reg3A has significantly suppressed tumor growth, highlighting its therapeutic potential." (PMID 39857608, 2024). "In colon cancer, high expression of Reg3A protein stimulated cell proliferation and tumorigenicity, resulting in larger tumor size, poor differentiation, and reduced survival rates." (PMID 39857608, 2024). "Tumor clusters 1, 2, and 3 were characterized by high expression of the known HB tumor markers REG3A, MEG3 and IGF28." (PMID 36008377, 2022).
tumor (continued). "Other studies have shown decreased REG3A expression in cancer cells as well as suppressed tumor growth." (PMID 34811636, 2022). "In Tumor Immune Estimation Resource database, we found that Reg3A is decreased in GC tissues (P < 0.01)." (PMID 34605357, 2021). "Among 88 HCC tumor tissues, the REG3A mRNA expression was upregulated in 46 samples (52.3%) as compared to non-tumor tissues, and positively correlated with PDGF-ββ (Pearson’s coefficient = 0.546; p < 0.001)." (PMID 31940813, 2020). "REG3A mRNA levels in human HCC tissues were upregulated 1.8-fold compared with non-tumor tissues and positively correlated with PDGF-ββ levels." (PMID 31940813, 2020). "The mean mRNA expression of REG3A was upregulated 1.8-fold in HCC tissues compared with non-tumor tissues (p = 0.05)." (PMID 31940813, 2020). "The results from the present study indicate that REG3A/p42/44 pathway/PDGF-ββ signaling plays a significant role in hepatocarcinogenesis via tumor-stroma crosstalk." (PMID 31940813, 2020). "Reg3A has long been believed as a potent proliferation promotor in non-tumor cells, including epidermal keratinocytes, insulin-positive cells in pancreatic tissues and hepatocytes." (PMID 31921694, 2019). "Then we revealed that REG3A expression levels were significantly correlated with tumor size, differentiation and grade, suggesting that REG3A overexpression is positively correlated with CRC progression." (PMID 26646797, 2016). "After 46 days, the volume and weight of REG3A shRNA1 treated tumor was significantly smaller and lighter than that of control (P < 0.01)." (PMID 26646797, 2016). "A multivariate Cox regression analysis confirmed REG3A expression, tumor size, and differentiation as independent predictors of the overall survival in CRC patients." (PMID 26646797, 2016). "Further, according to the relative REG3A protein expression in tumor tissues, the 82 CRC patients were classified into two groups: relative high group (n = 52) and relative low group (n = 30)." (PMID 26646797, 2016). "Further, high REG3A expression level was correlated with bigger tumor size, poorer differentiation, higher tumor stage and lower survival rate." (PMID 26646797, 2016). "The expression levels of REG3A determined using qRT-PCR agreed with the microarray data in tumor samples." (PMID 24573535, 2014). "Furthermore, by modulating host–microbiota interactions, REG3A contributes to shaping tumor immunity and systemic inflammation, broadening its relevance in cancer biology and targeted therapy." (PMID 40723277, 2025). "Additionally, endogenous overexpression of Reg3A enhanced T-cell infiltration, contributing to tumor suppression." (PMID 39857608, 2024). "Further clarifying the characterization of REG3A may lead to a better understanding of tumor development and progression and indicate a potential target for clinical treatment." (PMID 34811636, 2022). "Contradictory roles of REG3A have been reported in different tumor models." (PMID 34811636, 2022). "Interestingly, REG3A knockdown substantially arrests tumor cells in the G1 phase of the cell cycle, inhibits cell proliferation, suppresses cell migration, and promotes apoptosis in CRC cells." (PMID 35432477, 2022). "REG3A has long been studied as a proliferation-promoting factor in several non-tumor cells." (PMID 34811636, 2022). "Thus, contradictory roles of REG3A in modulating tumor development and progression have been noted in different tumor models." (PMID 34811636, 2022). "As a PC-derived factor, regenerating islet-derived protein 3A (Reg3A) could inhibit the differentiation and maturation of tumor-infiltrating DCs via the Reg3A-JAK2/STAT3 signaling pathway." (PMID 35619702, 2022). "In conclusion, Reg3A may act as a novel tumor suppressor by promoting DMBT1 expression, which may be a potential therapeutic target in patients with GC." (PMID 34605357, 2021). "Considering the clues above, we hypothesized that Reg3A acts as a tumor suppressor by targeting DMBT1 in GC." (PMID 34605357, 2021).
tumor (continued). "Moreover, the expression levels of LEP, DLX2, CLSTN2, and REG3A were significantly higher in tumor tissues than normal tissues." (PMID 33194689, 2020). "From this perspective, REG3A might promote tumor cells proliferation, but suppress metastatic cascade indirectly." (PMID 33194689, 2020). "Furthermore, the mRNA and protein expression levels of endogenous Reg3A in HPDE6c7 cells were shown to be enhanced by the stimulation of interleukin-6, a well-known cytokine playing a key role in tumor-promoting effect of inflammation." (PMID 31921694, 2019). "Moreover, Reg3A expression level was markedly correlated with the tumor size, differentiation or tumor stage." (PMID 31921694, 2019). "However, Reg1A and Reg3A/G positive duct-like structures were observed in tumor-adjacent acinar areas." (PMID 27788482, 2016). "Interestingly, Fisher's exact test indicated that REG3A expression level was significantly correlated with tumor size (P = 0.0211), differentiation (P = 0.0213) and tumor stage (P = 0.0186), but not gender or age." (PMID 26646797, 2016). "Furthermore, some studies report a negative correlation between REG3A expression and tumor progression in specific settings, suggesting that REG3A may act as a tumor suppressor under certain conditions while promoting tumor growth in others." (PMID 40723277, 2025). "Thus, we speculated about the potential relationship between REG3A overexpression and uncontrolled tumor growth." (PMID 34811636, 2022). "Therefore, based on its intrinsic proliferation-promoting activity, Reg3A over-expressed in gastrointestinal cancer could be speculated to allow uncontrolled tumor growth." (PMID 31921694, 2019). "However, more research is required to determine whether Reg3A as a new biomarker provide an advantage on existing tumor markers." (PMID 31921694, 2019). "Therefore, Reg3A could be used as a tumor biomarker for gastrointestinal malignancy and as a promising target for prevention and treatment." (PMID 31921694, 2019). "Notably, Reg3A might be not only useful as a promising tumor marker, but also play a potential key role in the initiation and progression of gastrointestinal malignancy." (PMID 31921694, 2019). "Next, we explored whether silence of REG3A in CRC cells could suppress tumor growth in vivo." (PMID 26646797, 2016). "We identified 1,758 HB-specific and 1,803 non-tumor-specific TAD boundaries, containing 81 and 108 DEGs, respectively, such as TDGF1, TNFSF4, and REG3A." (PMID 41462308, 2025). "Hence, we hypothesized that Reg3A is a tumor suppressor in GC." (PMID 34605357, 2021). "The novel finding of this present study is that the REG3A mRNA and protein expression levels were significantly enhanced in HCC cells as a result of crosstalk between tumor and stroma." (PMID 31940813, 2020). "Tumor growth induced when coculturing HCC cells and HSCs was also significantly inhibited following REG3A siRNA transfection in Group 2 (REG3A siRNA transfected MH134 cell + LX-2 coculturing) compared with Group 1, especially at D7 (p < 0.05)." (PMID 31940813, 2020). "The expression of REG3A was further determined in resected HCC and adjacent non-tumor tissues using qRT-PCR." (PMID 31940813, 2020). "Proliferating tumor cells in early stage PDAC express REG1A, REG1B, REG3A, and REG4 and throughout PDAC development." (PMID 31696115, 2019). "This is in agreement with our previous study showing that REG3A accelerated tumor growth via STAT3 signaling, and with our present findings indicating that Reg3g promoted tumor growth by suppressing immune responses." (PMID 28880262, 2017). "In cholangiocarcinoma, REG3A is markedly overexpressed in tumor tissues relative to adjacent non-neoplastic bile duct epithelium, suggesting a possible role in tumor initiation or maintenance." (PMID 40723277, 2025). "Notably, REG3A has been identified as a positive regulator of DMBT1, potentially counteracting H. pylori-mediated silencing of this tumor suppressor." (PMID 40723277, 2025).
tumor (continued). "One large-scale analysis of 331 matched tumor–normal tissue pairs found REG3A to be enriched in tumors lacking deep invasion, with high expression correlating with improved overall survival." (PMID 40723277, 2025). "The activation of REG3A will enhance JAK2/STAT3 pathway, amplify the carcinogenic effect of IL-6/JAK2/STAT3, and ultimately leads to excessive PC cell proliferation in vitro and in vivo and tumor formation." (PMID 36591515, 2022). "The results from the current study support this hypothesis and indicate REG3A might be the key targeting molecule activated by crosstalk between HCC cells and tumor stroma." (PMID 31940813, 2020). "The results confirmed the enhancing effect of Reg3A on PNI and tumor aggressiveness." (PMID 31921694, 2019). "Notably, REG3A is primarily secreted by peritumoral pancreatic acinar cells rather than by tumor cells themselves." (PMID 40723277, 2025). "REG1A, REG3A, and REG3G expression is not observed in normal acini and ducts but is detectable in tumor-adjacent acinar areas." (PMID 31696115, 2019).